SBF1 (SET binding factor 1)
Description:
Acts as an adapter for the phosphatase MTMR2 to regulate MTMR2 catalytic activity and subcellular location. Promotes the exchange of GDP to GTP, converting inactive GDP-bound Rab proteins into their active GTP-bound form. May function as a guanine nucleotide exchange factor (GEF) activating RAB28. Acts as a suppressor of autophagy in neurons. Together with its binding partner, the phosphatase MTMR2, plays a role in dephosphorylation of phosphoinositides critical for autophagy initiation and autophagosome maturation. Plays a role in positively regulating late-stage radial sorting of large caliber axons, a process leading to myelination by Schwann cells, possibly via regulating endosomal trafficking (By similarity). Inhibits myoblast differentiation in vitro and induces oncogenic transformation in fibroblasts.
Synonyms: MTMR5; DENND7A; CMT4B3
Tractability: PROTAC: ubiquitination databases record sites on it; its protein half-life has been measured.
Gene: Protein-coding gene on chromosome 22 (50,443,219 to 50,483,923, reverse strand). Ensembl gene ENSG00000100241.
Subcellular location: Cytoplasm; Cytoplasm, perinuclear region; Cell projection, neuron projection
Subcellular location (Human Protein Atlas): Nuclear bodies
Pathways (Reactome):
Metabolism: Synthesis of PIPs at the ER membrane
Vesicle-mediated transport: RAB GEFs exchange GTP for GDP on RABs
Gene Ontology:
Molecular function: guanyl-nucleotide exchange factor activity; phosphatase activity; protein binding; protein-membrane adaptor activity; protein tyrosine/serine/threonine phosphatase activity
Biological process: phosphatidylinositol biosynthetic process; protein dephosphorylation; spermatid development
Cellular component: cytoplasm; nuclear body; cytosol; endoplasmic reticulum membrane; membrane; neuron projection; perinuclear region of cytoplasm
Genetic constraint (gnomAD): Loss-of-function variants: 65 observed, 209.83 expected, observed/expected ratio (o/e) 0.31, 90% interval 0.25 to 0.38. The synonymous counts are far from expectation, so gnomAD's model fits this gene poorly and the ratio says little. Missense variants: 2,634 observed, 2,641.2 expected, observed/expected ratio (o/e) 1, 90% interval 0.96 to 1.03. Synonymous variants: 1,410 observed, 1,111.1 expected, observed/expected ratio (o/e) 1.27, 90% interval 1.21 to 1.33.
Gene-disease validity (ClinGen):
ClinGen rates the evidence that SBF1 causes each of these diseases.
Charcot-Marie-Tooth disease type 4B3 (autosomal recessive): Moderate.
Homologues: Orthologues: chimpanzee SBF1 (99% identical), macaque SBF1 (98% identical), dog SBF1 (95% identical), rat Sbf1 (95% identical), guinea pig SBF1 (95% identical), mouse Sbf1 (95% identical), pig SBF1 (95% identical), tropical clawed frog sbf1 (72% identical), zebrafish sbf1 (70% identical), Drosophila melanogaster Sbf (43% identical), Caenorhabditis elegans mtm-5 (23% identical), Caenorhabditis elegans mtm-3 (12% identical), and 9 more. Paralogues in human: SBF2 (58% identical), MTMR3 (12% identical), MTMR4 (11% identical), MTMR2 (10% identical), MTMR1 (10% identical), MTMR7 (10% identical), MTM1 (10% identical), MTMR6 (9% identical), MTMR10 (9% identical), MTMR8 (9% identical), MTMR9 (8% identical), MTMR11 (8% identical), and 1 more.
Diseases named in the same sentence as SBF1 in open-access papers:
SBF1 is named in the same sentence as 28 diseases in open-access papers, as found by Europe PMC text mining. Sharing a sentence is not in itself a finding about the gene and the disease. The quoted sentences say what the papers report.
neuropathy (3 papers, 2020 to 2025). A disorder affecting the nervous system that manifests with pain, tingling, numbness, and/or muscle weakness. "Mutations in some phosphoinositide metabolism genes (FIG4, PTEN, MTMR2, and SBF1) also cause neuropathies with conduction slowing and/or CB,26, 27, 28 suggesting a more fundamental role of GPI in the pathophysiology of this inherited neuropathy, independent of the GPI‐APs that are affected." (PMID 39444079, 2025). "We reported a novel homozygous frameshift deletion in SBF1 in a family affected with a rare form of neuropathy with necklace fibres on the muscle biopsy." (PMID 32444983, 2020). "In this study, a novel frameshift deletion in SBF1 was identified in two siblings with complex neuropathy and “necklace fibres” in muscle biopsy, expanding the spectrum of SBF1-related syndromic neuropathy." (PMID 32444983, 2020).
Alzheimer disease (2 papers, 2022 to 2025). A progressive, neurodegenerative disease characterized by loss of function and death of nerve cells in several areas of the brain leading to loss of cognitive function such as memory and language. "The human SBF1 (SET binding factor 1) gene, alternatively known as MTMR5, is predominantly expressed in the brain, and its epigenetic dysregulation is linked to late-onset neurocognitive disorders (NCDs), such as Alzheimer’s disease." (PMID 36104480, 2022).
Charcot-Marie-Tooth disease (2 papers, 2021 to 2023). An inherited degenerative disorder involving the peripheral nerves. "Charcot-Marie-Tooth disease (CMT) type 4B3 (CMT4B3) is a rare form of genetic neuropathy associated with variants in the MTMR5/SBF1 gene." (PMID 34118926, 2021).
Charcot-Marie-Tooth disease type 4B3 (2 papers, 2015 to 2025). "SBF1 is associated with demyelinating peripheral neuropathy and Charcot-Marie-Tooth disease type 4B3 (OMIM: 615284)." (PMID 26547235, 2015).
axonal motor neuropathy (1 paper, 2021). "We report the case of an Italian girl with progressive and severe infantile-onset axonal motor neuropathy and biochemical features suggestive of mitochondrial disease in whom next-generation sequencing studies allowed us to identify biallelic variants in MTMR5/SBF1." (PMID 34118926, 2021).
cervical cancer (1 paper, 2014). A primary or metastatic malignant neoplasm involving the cervix. "In human cervical cancer cells, ER Ca2+ homeostasis is disrupted and ER stress-mediated cell death is induced by SBF-1 both in vitro and in vivo." (PMID 25522275, 2014).
coronary heart disease (1 paper, 2024). "While, the relationship between SBF1 and coronary heart disease need further validation." (PMID 38715006, 2024).
epilepsy (1 paper, 2023). A brain disorder characterized by episodes of abnormally increased neuronal discharge resulting in transient episodes of sensory or motor neurological dysfunction, or psychic dysfunction. "The clinical evidence of epilepsy in patients with CMT and hypermethylation of SBF1 in patients with Drug-resistant Temporal Lobe Epilepsy highlights the role of the SBF1 gene in epilepsy." (PMID 38002941, 2023).
leukemia (1 paper, 2010). A malignant (clonal) hematologic disorder, involving hematopoietic stem cells and characterized by the presence of primitive or atypical myeloid or lymphoid cells in the bone marrow and the blood. "However, mutations in SID impeding its binding to SET result in abnormal growth and leukemia and the inactive myotubularin Sbf1 has been isolated as a component of the Trx complex, physically and functionally linked with the trithorax protein in Drosophila." (PMID 20967218, 2010).
male infertility (1 paper, 2020). The inability of the male to effect fertilization of an ovum after a specified period of unprotected intercourse. "Loss of function of MTMR5 was suggested to cause a defect in the late stages of spermatogenesis in mice and studies on humans showed that rare variants in SBF1 are linked to male infertility." (PMID 32444983, 2020).
paraplegia (1 paper, 2014). Complete paralysis of the lower half of the body including both legs, often caused by damage to the spinal cord. "A further two Rabs showed strong and specific interactions with membrane traffic machinery that we did not validate because of a lack of suitable reagents: Rab26 with the spastic paraplegia proteins Spg11 and Spg15 (also found with Rab7), and Rab35 with the Rab GEF Sbf (SBF1/2 in humans)." (PMID 25453831, 2014).
sensory neuropathies (1 paper, 2022). "Mutations in the human SBF1 gene were identified to cause motor and sensory neuropathies." (PMID 36614124, 2022).
neurological disorders (5 papers, 2017 to 2025). "In this cohort, seven genes have already been associated with neurological disorders (MNX1, NINJ1, PER2, PHF20, PRSS56, RPH3A, and SBF1) in MalaCards and OMIM." (PMID 28769055, 2017).
tumor (3 papers, 2019 to 2025). "Using RPL19-TRAPKI-seq, we found that SBF-1 exerts its cytotoxic effects on tumor cells by disturbing cellular oxidative phosphorylation." (PMID 40042546, 2025). "Taken together, the in vivo study strongly suggested that blocking mitochondrial localization of HIBCH by SBF-1 could be effective in inhibiting tumor growth in CRC xenograft models." (PMID 31409769, 2019).
peripheral neuropathy (2 papers, 2024 to 2025). A disorder affecting the peripheral nervous system. "Biallelic loss of expression/function variants in MTMR5/SBF1 cause the inherited peripheral neuropathy Charcot-Marie-Tooth type 4B3." (PMID 40066109, 2025). "In this study, a novel missense mutation in the SBF1 gene was identified in a heterozygote mother and daughter with complex peripheral neuropathy, demonstrating that this mutation could alter the inheritance pattern and induce autosomal dominant inheritance of CMT4B3." (PMID 39664754, 2024).
cancer (1 paper, 2019). A tumor composed of atypical neoplastic, often pleomorphic cells that invade other tissues. "In this study, we addressed how SBF-1, which exhibits a strong antitumor activity in various cancer types, regulated the inflammatory process leading to contact hypersensitivity pathogenesis." (PMID 31864413, 2019).
SBF1 also shares sentences with these, for which no sentence is quoted: autism (2 papers); centronuclear myopathy (2); polyneuropathy (2); X-linked centronuclear myopathy (2); demyelinating peripheral neuropathy (1); glaucoma (1); Intellectual disability (1); maple syrup urine disease (1); microcephaly (1); mitochondrial disease (1); neuromuscular disease (1); temporal lobe epilepsy (1).